ENSG00000249945 (novel transcript)
Gene: Long non-coding RNA gene on chromosome 4 (175,457,726 to 175,473,197, reverse strand). Ensembl gene ENSG00000249945.
Gene Ontology:
Biological process: miRNA-mediated post-transcriptional gene silencing